ACSL4 (acyl-CoA synthetase long chain family member 4)
Diseases named in the same sentence as ACSL4 in open-access papers (continued):
Sharing a sentence is not in itself a finding about the gene and the disease.
epilepsy (5 papers, 2019 to 2025). A brain disorder characterized by episodes of abnormally increased neuronal discharge resulting in transient episodes of sensory or motor neurological dysfunction, or psychic dysfunction. "Treatment with pioglitazone, a recently discovered ACSL4 inhibitor, abrogated the increased risk of epilepsy." (PMID 31191222, 2019). "Consistent with our findings, we observed abnormal expression of ferroptosis‐related proteins ACSL4, PTGS2, and GPX4 in the hippocampal tissues of KA‐induced epileptic mice, indicating the involvement of ferroptosis in epilepsy." (PMID 39957487, 2025). "Activation of the HIF-1α/H -1 pathway is evident as hippocampal neurons in epileptic animal models and epilepsy patients’ brain tissues show marked HIF-1α and HO-1 upregulation, positively correlating with ferroptosis markers like lipid peroxides, ACSL4 increase, and GPX4 inactivation." (PMID 40421132, 2025).
heart failure (5 papers, 2022 to 2025). Inability of the heart to pump blood at an adequate rate to meet tissue metabolic requirements. "Recent study has also found that in cardiomyocytes, ACSL4-dependent ferroptosis drives activation of pyroptosis, causing heart failure." (PMID 40000618, 2025). "In heart failure, the expression of ACSL4 in cardiomyocytes was elevated, which was shown to trigger ferroptosis and aggravate the cardiac hypertrophy by activating pyroptotic signaling." (PMID 40000618, 2025). "Here, we report that both the production of PEs and ACSL4 expression significantly increase in pressure overload-induced heart failure." (PMID 39327446, 2024). "Together, these findings provide compelling evidence that targeting the ACSL4-ferroptosis-pyroptotic signaling cascade may provide a promising therapeutic strategy for preventing heart failure." (PMID 39327446, 2024). "In addition, ACSL4 has been reported in studies related to AMI, while miR-590-5p has been shown to inhibit pathological hypertrophy-mediated heart failure." (PMID 35231061, 2022).
Hyperglycemia (5 papers, 2014 to 2025). An increased concentration of glucose in the blood. "Furthermore, in diabetic wound-healing models, hyperglycemia-induced SQSTM1 loss impairs autophagic flux, leading to ACSL4 accumulation and enhanced ferroptosis." (PMID 40843317, 2025). "Here, we provide the first evidence that in DR, hyperglycemia causes endothelial dysfunction via activating ferroptosis and ZFAS1/miR-7-5p/ACSL4 axis may serve as a key signaling in ferroptosis process." (PMID 36092160, 2022). "Moreover, our data showed that hyperglycemia caused changes in ferroptosis-related markers, including GPX4, ACSL4, iron, and MDA levels, in diabetic rats." (PMID 36290619, 2022). "Altogether, we found that the lncRNA ZFAS1 was induced by hyperglycemia in hRECs and proposed that ZFAS1 may exerts its role by competitively binding with miR-7-5p and modulating the expression of its downstream mRNA ACSL4 expression." (PMID 36092160, 2022).
Intellectual disability (5 papers, 2015 to 2023). "Mutation of the human ortholog ACSL4 (acyl-CoA synthase long chain family member 4) causes non-syndromic X-linked mental retardation." (PMID 26398944, 2015). "It is noteworthy that ferroptosis was not mentioned in studies that suggested ACSL4 gene dysfunction leads to intellectual disability." (PMID 36507355, 2022).
metabolic syndrome (5 papers, 2022 to 2025). A cluster of metabolic risk factors for CARDIOVASCULAR DISEASES and TYPE 2 DIABETES MELLITUS. "In addition, ACLS4 was previously proposed as a candidate gene associated with metabolic syndrome (MetS), and the common single nucleotide polymorphism (C to T substitution in the first intron) of ACSL4 unfavorably alters the fatty acyl profiles of plasma phosphatidylcholines (PCs) in MetS patients." (PMID 39872215, 2024). "STZ treatment also upregulated long‐chain acyl‐CoA synthetase 4 (ACSL4), promoting the accumulation of polyunsaturated fatty acids, such as arachidonic acid, further contributing to dyslipidemia." (PMID 40279648, 2025). "Here, Acsl4 significantly increased in the IUGR compared with AGA, which indicated that upregulated Acsl4 might be involved in the development of metabolic syndrome." (PMID 35321016, 2022). "Furthermore, one DEC from 45,X vs. 46, XX in fat, which is derived from ACSL4, may be involved in fatty acid metabolism and metabolic syndrome." (PMID 35938026, 2022).
non-alcoholic steatohepatitis (5 papers, 2023 to 2025). "An epigenetics study on non-alcoholic steatohepatitis (NASH) found hypomethylation of the ACSL4 gene in peripheral blood lymphocytes, leading to its overexpression and suggesting its potential as a biomarker for NASH-associated ferroptosis." (PMID 40932861, 2025). "In mouse models of non-alcoholic steatohepatitis, they were targeting hepatic ACSL4 improved liver health, highlighting its role in metabolic diseases." (PMID 39906302, 2025). "Arsenic also triggers nonalcoholic steatohepatitis (NASH) by inducing ferroptosis via the Mfn2/IRE1α-ACSL4 pathway, contributing to the lipid metabolism disturbances associated with NASH." (PMID 40666111, 2025).
ulcerative colitis (5 papers, 2022 to 2025). An inflammatory bowel disease involving the mucosal surface of the large intestine and rectum. "In this study, the expression of ferroptosis biomarker ACSL4 increased, the expression of GPX4 and FTH1 decreased, and the expression of HO-1 decreased in the PFOS group, results consistent with the study of Yeru Chen on the relationship between ferroptosis and ulcerative colitis." (PMID 36136468, 2022).
acute pancreatitis (4 papers, 2024 to 2026). An acute inflammatory process that leads to necrosis of the pancreatic parenchyma. "A recent study reported that METTL14 up-regulation promotes pancreatic cell inflammation and ferroptosis by increasing ACSL4 expression in an N6-methyladenosine-dependent manner in severe acute pancreatitis." (PMID 40785592, 2025). "Further screening identified four genes (ACSL4, GALNT3, WSB1, and IL1R1) that were significantly upregulated in severe acute pancreatitis (SAP) in both human and mouse samples." (PMID 38862656, 2024). "In the in vitro experiments, we discovered for the first time that ferroptosis occurs in pancreatic duct cells during acute pancreatitis, and that MGST1 is significantly upregulated in duct cells, where it plays a crucial role in negatively regulating ferroptosis via the ACSL4/GPX4 axis." (PMID 40076525, 2025).
cerebral infarction (4 papers, 2021 to 2026). An ischemic condition of the brain, producing a persistent focal neurological deficit in the area of distribution of the cerebral arteries. "Previous studies have suggested that ACSL4 may be a target for the inhibition of ferroptosis; we explored the mechanism of ACSL4 in cerebral infarction in more detail." (PMID 33889074, 2021).
Cognitive impairment (4 papers, 2021 to 2023). Abnormal cognition is characterized by deficits in thinking, reasoning, or remembering. "ACSL4 has a preference for ARA, forming ARA-CoA, which is incorporated into lysophospholipids by lysophospholipid acyl transferases and has also been associated with cognitive impairment and, in a few cases, neuroprotection." (PMID 37744400, 2023). "Inhibiting the expression of ACSL4 using small interfering RNAs alleviated inflammation, blood‐brain barrier (BBB) impairment, oxidative stress, brain edema, and behavioral and cognitive deficits, and increased the number of surviving neurons, after SAH." (PMID 33314758, 2021). "The level of ACSL4 in the brain tissue of rats with SAH was significantly increased; however, the use of siRNA to inhibit the expression of ACSL4 alleviated inflammation, BBB damage, brain edema, and behavioral and cognitive impairment after SAH by promoting neuronal survival." (PMID 35481263, 2022).
head and neck cancer (4 papers, 2020 to 2023). A primary or metastatic malignant neoplasm affecting the head and neck. "It has been shown that ACSL4 is a target of miR-106b-5p in brain microvascular endothelial cells, and miR-106 has been demonstrated to enhance radiation sensitivity of head and neck cancers." (PMID 35328568, 2022). "In this manuscript, we have summarized how these non-coding RNAs are implicated in various aspects of ferroptosis in head and neck cancers including iron metabolism (Mfrn1/2, LOX, TfR1, and LTF), lipid metabolism (LKB1 and ACSL4), and ROS accumulation (SLC3A2, SLC7A11, ATF3, Nrf2, and GPX4)." (PMID 35328568, 2022). "It has been described that GPX4, xCT and ACSL-4 are the main targets in the regulation of ferroptosis and GPX4 is the key in the ferroptosis of head and neck carcinoma cells." (PMID 32452511, 2020).
injury (4 papers, 2022 to 2025). Damage inflicted on the body as the direct or indirect result of an external force, with or without disruption of structural continuity. "Moreover, our study also showed that YAP1 promoted the expression of SLC7A11 and increased the GPX4 and GSH level both in septic liver injury mice and LPS-stimulated LO2 cells, while suppressed the expression of ACSL4." (PMID 36182901, 2022).
kidney damage (4 papers, 2017 to 2025). "Additionally, because we focused on the 24 h reperfusion time point, when kidney damage had begun and was accompanied by a clear window between ACSL4 levels in Mlkl-knockout and wt mice, we stopped the therapy with 16–86 24 h after the onset of reperfusion." (PMID 28551825, 2017). "In vivo, administration of ox-Alb exacerbated doxorubicin-induced nephropathy, as indicated by the elevated BUN, creatinine, and proteinuria, and intensified renal ferroptotic responses, including altered GPX4 and ACSL4." (PMID 40649703, 2025).
non-alcoholic fatty liver disease (4 papers, 2022 to 2024). "A previous study also found that hypomethylated CpG sites of ACSL4 were associated with an increased risk of non-alcoholic fatty liver disease (NAFLD)." (PMID 35126480, 2022). "Hepatic ACSL4 levels are elevated in patients with non-alcoholic fatty liver disease, and suppression of hepatic ACSL4 reduces hepatic lipid accumulation by promoting mitochondrial respiration and β-oxidation of fatty acids." (PMID 39872215, 2024).
osteoarthritis (4 papers, 2021 to 2025). A noninflammatory degenerative joint disease occurring chiefly in older persons, characterized by degeneration of the articular cartilage, hypertrophy of bone at the margins and changes in the synovial membrane. "Recent study also elicited that peroxisome ATP binding cassette, subfamily D, member 2 (ABCD2), in osteoarthritis chondrocytes can affect miR-141 expression, downregulate the expression of acyl-CoA synthetase 4 (ACSL4), and thus induce the accumulation of very long chain fatty acids (VLCFAs)." (PMID 34659401, 2021).
prostate tumor (4 papers, 2021 to 2025). "All together, our findings reveal the regulation of ferroptosis by the RB/E2F/ACSL4 axis and highlight the therapeutic potential of ferroptosis induction in the treatment of RB1 loss–driven prostate tumor growth and metastasis and perhaps other RB1-deficient malignancies." (PMID 36928314, 2023).
psoriasis (4 papers, 2021 to 2026). An autoimmune condition characterized by red, well-delineated plaques with silvery scales that are usually on the extensor surfaces and scalp. "The expression of GPX4 and ACSL4 were detected in psoriasis lesions and normal samples by immunohistochemistry." (PMID 34707088, 2021).
acute myeloid leukemia (3 papers, 2024 to 2025). Acute myeloid leukemia (AML) is a group of neoplasms arising from precursor cells committed to the myeloid cell-line differentiation. "Knockdown of ACSL4 decreases dihomo-γ-linolenic acid (DGLA)-induced ferroptosis sensitivity in acute myeloid leukemia (AML) cells." (PMID 41288931, 2025).
Anxiety (3 papers, 2013 to 2023). Intense feelings of nervousness, tension, or panic often arise in response to interpersonal stresses. "Based on DisgeNet data, Acsl4, Clock, Scn2a, and Hivep2 are confirmed as anxiety-related genes." (PMID 36979479, 2023). "Then, we found the proteins expression of GPX4, SLC7A11, FTH, ACSL4 and FPN, which were also significantly reduced in depressive and anxiety-like behavioral mice whose symptoms were induced by alcohol." (PMID 36430312, 2022).
bipolar disorder (3 papers, 2013 to 2022). A disorder of the brain that causes unusual shifts in mood, energy, activity levels and the ability to carry out day-to-day tasks. "For example, mood stabilizer valproic acid and chiral isomer valnoctamide have been shown to take effect in the treatment of bipolar disorder by inhibiting recombinant ACSL4, brain AA turnover in brain phospholipids, and AA activation to AA-CoA." (PMID 36507355, 2022). "Valproic acid, which inhibits rat brain microsomal ACSL4, reduces arachidonic acid turnover; this suggests a possible mechanism that might account for the efficacy of valproic acid in treating bipolar disorder." (PMID 24066181, 2013). "Therefore, targeting ferroptosis-related protein ACSL4 may shed new light on the therapy of some other CNS diseases, including epilepsy, ALS, cerebral malaria, bipolar disorder, and sepsis-associated encephalopathy." (PMID 36507355, 2022).
Breast invasive carcinoma (3 papers, 2021 to 2022). "Specifically, ACSL4 is positively correlated with immune infiltration in the tumor microenvironment, which is intensively related to prognosis in breast invasive carcinoma and skin cutaneous melanoma." (PMID 35910359, 2022). "ACSL4 and immune infiltration are strongly associated with prognosis in BRCA (Breast invasive carcinoma) and SKCM (Skin Cutaneous Melanoma)." (PMID 35126480, 2022). "According to these studies, lower ACSL4 expression points more beneficial prognosis, and ACSL4 may serve as a promising prognostic biomarker for invasive breast cancer." (PMID 35910359, 2022).
chronic kidney disease (3 papers, 2022 to 2024). Impairment of the renal function secondary to chronic kidney damage persisting for three or more months. "Thus, targeting the STING/ACSL4 axis may be a potential approach to treating hypertension-associated chronic kidney disease (CKD)." (PMID 39769377, 2024). "Recently, several repurposing drugs have been identified that specifically inhibit ACSL4, such as Abemaciclib and PRGL493, but their potential role and/or side effects in ferroptotic-related diseases, especially in acute or chronic kidney diseases, remain to be further investigated." (PMID 37670055, 2023).
Cirrhosis (3 papers, 2020 to 2023). A chronic disorder of the liver in which liver tissue becomes scarred and is partially replaced by regenerative nodules and fibrotic tissue resulting in loss of liver function. "Furthermore, ACSL4 staining is useful to distinguish small clusters of HCC cells from a background of substantial cirrhosis and necrosis." (PMID 32286604, 2020). "A total of 97 HCC patients with cirrhosis were selected from TCGA, and 5 genes (ADH1C, ACSL4, GPD2, ME1, NCAPH2) were selected to construct a FAM-related prognosis signature via Lasso–Cox regression using this cohort." (PMID 36671526, 2023).
endothelial dysfunction (3 papers, 2022 to 2025). In vascular diseases, endothelial dysfunction is a systemic pathological state of the endothelium (the inner lining of blood vessels) and can be broadly defined as an imbalance between vasodilating and vasoconstricting substances produced by (or acting on) the endothelium. "Our animal and cellular results consistently disclosed that Hamaudol treatment significantly improved endothelial dysfunction under diabetic state by restoring NKAα1 protein expression and inhibiting ACSL4‐mediated ferroptosis." (PMID 39902679, 2025). "In conclusion, our results demonstrate that HG-induced ZFAS1 elevation activates ferroptosis in hRECs and the ZFAS1/miR-7-5p/ACSL4 axis may serve as a therapeutic target for endothelial dysfunction in DR." (PMID 36092160, 2022). "Taken together, these results imply that ZFAS1 may modulate ferroptosis-mediated endothelial dysfunction through ACSL4, a well-recognized promotor of ferroptosis, by sponging miR-7-5p." (PMID 36092160, 2022). "In PFOS-induced vascular diseases studied here, ferroptosis-related pathways were activated, GPX4 was down-regulated, and ACSL4 was up-regulated, resulting in increased lipid reactive oxygen species levels, triggering iron death in endothelial cells and eventually leading to endothelial dysfunction." (PMID 36136468, 2022).
Hypertension (3 papers, 2023 to 2025). The presence of chronic increased pressure in the systemic arterial system. "In mice with high-salt-induced hypertension, there was a significant increase in the protein and mRNA expression of ACSL4 and LPCAT3, along with a decrease in GPX4 expression (p < 0.001)." (PMID 41019540, 2025). "In summary, our study preliminarily showed that hypertension induces intracellular PUFAs to bind to phospholipids under the catalysis of ACSL4 and LPCAT3 to form PL–PUFAs, which are further oxidized by ALOX15, resulting in the accumulation of lipid peroxides." (PMID 39595632, 2024). "Stimulator of interferon genes (STING) regulates renal inflammatory response and fibrosis induced by hypertension through acyl-CoA synthetase long chain family member 4 (ACSL4)-mediated fibroblasts." (PMID 38239871, 2023).
Insulin resistance (3 papers, 2022 to 2025). Increased resistance towards insulin, that is, diminished effectiveness of insulin in reducing blood glucose levels. "Upregulation of ACSL4 expression was observed in mice fed a high-fat diet, and when ACSL4 was specifically knocked out in adipocytes in mice fed a high-fat diet, the mice were protected from insulin resistance." (PMID 36160012, 2022).
kidney cancer (3 papers, 2022 to 2025). Primary or metastatic malignant neoplasm involving the kidney. "We aimed to explore the relationship between SPI1 and ACSL4 in kidney cancer tissue samples." (PMID 41372608, 2025). "SPI1 synergistically promotes the inhibition of lipid peroxidation in kidney cancer cells with the epigenetic molecule EZH2, and its target is ACSL4, a key molecule for ferroptosis." (PMID 41372608, 2025).
mesothelioma (3 papers, 2021 to 2023). A usually malignant and aggressive neoplasm of the mesothelium which is often associated with exposure to asbestos. "Studies have shown that YAP pathway activation in mesothelioma tissue enhances iron death sensitivity through ACSL4 and TFRC, and YAP, ACSL4, and TFRC are expected to be biological markers for clinical prediction of iron death sensitivity in mesothelioma." (PMID 35906548, 2022).
metastatic melanoma (3 papers, 2019 to 2026). A melanoma that has spread from its primary site to another anatomic site. "Notably, metastatic melanoma cases exhibited higher ACSL4 expression than non-metastatic cases; however, within cutaneous melanoma, elevated ACSL4 remained linked to more favorable survival outcomes." (PMID 41918944, 2026).
pancreatic ductal adenocarcinoma (3 papers, 2022 to 2025). An infiltrating adenocarcinoma that arises from the epithelial cells of the pancreas. "The knockdown of PIR increased mRNA levels of ACSL4, a biomarker and a key promoter of ferroptosis, in pancreatic ductal adenocarcinoma cell lines." (PMID 36467089, 2022). "Cancer-associated fibroblasts (CAFs) exosome-derived miR-3173-5p sponged ACSL4 and suppressed ferroptosis, resulting in gemcitabine (GEM) resistance in pancreatic ductal adenocarcinoma (PDAC)." (PMID 38534739, 2024).